CRP (C-reactive protein)
Diseases named in the same sentence as CRP in open-access papers (continued):
Sharing a sentence is not in itself a finding about the gene and the disease.
influenza (156 papers, 2010 to 2026). An acute viral infection of the respiratory tract, occurring in isolated cases, in epidemics, or in pandemics; it is caused by serologically different strains of viruses (influenzaviruses) designated A, B, and C, has a 3-day incubation period, and usually lasts for 3 to 10 days. "CONCLUSION: NEWS2, CRB-65, CRP, and white blood cell count were independently associated with antibiotic initiation in adults with influenza, while only CRP predicted bacterial coinfection." (PMID 41877014, 2026). "Higher CRP and procalcitonin blood levels were associated with antibiotic treatment more frequently, while positive influenza PCR results were associated with lower antibiotic prescriptions." (PMID 40001364, 2025). "A systematic review of the literature concluded that SARS-CoV-2 infections cause less increase in CRP and procalcitonin values when compared with influenza." (PMID 40430211, 2025). "Similar to our finding, elevated CRP level was associated with influenza infection in respirator tracts." (PMID 38249383, 2023). "The duration of fever in Chinese influenza patients is closely associated with fever on day 1 and CRP level, and symptom cycle is closely related to monocyte counts and sex." (PMID 38088961, 2023). "In a clinical scenario of an infant with undifferentiated fever most paediatricians reported that they would use some kind of diagnostic tests with urine dipsticks, CRP, and influenza being the most commonly cited POCTs in both settings." (PMID 36538525, 2022). "The results suggested that deficiency of CRP or human CRP transgenic treatment decreased IL-17 immune response in influenza infection." (PMID 36275680, 2022). "Point of care or rapid diagnostic (office-based) tests (e.g., C-reactive protein; influenza antigens, group A streptococcal antigen) were discussed in 11 papers." (PMID 32784918, 2020). "Although the present study is the first systematic review for the association between CRP and severity of influenza, it has several limitations." (PMID 30288556, 2019). "ROC curve analysis revealed showed that CRP ≥ 7.57 mg/L, Serum IL-6 ≥ 9.84 pg/ml, days from onset of Flu symptoms to hospitalization ≤4.5 days, CSF-TP ≥ 194.80 mg/L and FluA increased the risk of severe influenza combined with febrile seizures." (PMID 39507495, 2024). "In this study, CRP ≥ 7.57 mg/L, IL-6 ≥ 9.84 pg/ml, Days from onset of Flu symptoms to hospitalization ≤4.5 days, CSF-TP ≥ 194.8 mg/L, and FluA were found to be independent risk factors for severe influenza combined with febrile seizures." (PMID 39507495, 2024). "Despite causing only a slight elevation in C-reactive protein, which resolves completely within 14 days, influenza vaccination has been associated with abnormalities in arterial function, as measured by a decrease in flow-mediated dilation for at least 2 weeks after vaccination." (PMID 39835131, 2024). "Furthermore, both PCT and CRP are valuable prognostic markers with significant association with clinical outcomes and mortality in influenza and SARS-CoV-2 pneumonia." (PMID 36671362, 2023). "However, to our knowledge, it is unclear on the pathogenesis associated with CRP on severe influenza infection." (PMID 36275680, 2022). "We also aimed to examine the association between CRP and various influenza-like symptoms." (PMID 33174788, 2020). "Factors associated with C-reactive protein (CRP) ≥ 30 mg/L in patients with influenza-like illness." (PMID 33174788, 2020). "Furthermore, cytokine storm has been implicated previously both in severe H5N1 and H7N9 influenza where excessive immune activation, particularly the complement activation mediated by CRP, was reported." (PMID 30288556, 2019). "However, it is unclear on the pathogenesis associated with CRP in influenza infections." (PMID 36275680, 2022).
influenza (continued). "During Period 2, new point-of-care tests (POCTs), including rapid C-reactive protein and rapid antigen detection for Influenza A, Influenza B, and SARS-CoV-2, and a multiplex PCR nasal swab, were introduced." (PMID 41471239, 2025). "In our study, we confirmed a high prevalence of low 25-hydroxyvitamin D status, which depended on age, sex, sun exposure, prevalence of influenza, CRP and homocysteine levels." (PMID 40033138, 2025). "Clinical presentation typically included influenza-like symptoms, and laboratory data included elevated C-reactive protein (CRP) and white blood cell count (mainly neutrophilia) and an absence of radiological abnormalities." (PMID 40732017, 2025). "A previous study indicated that KD cases with influenza infections had a tendency towards elevated CRP levels and that influenza, assumedly, plays a role in the inflammatory response." (PMID 39941446, 2025). "Specifically, two classical immune-related pathways, the “Role of Hypercytokinemia/hyperchemokinemia in the Pathogenesis of Influenza” and the “IL-33 Signalling Pathway”, are activated in the CRP 1–3 group vs. >3." (PMID 39271754, 2025). "Another study revealed a significantly greater incidence of severe influenza in children with a CRP > 8 mg/L and concluded that elevated CRP levels correlate with disease severity." (PMID 39507495, 2024). "In this study, we show a negative correlation between HDL plasma concentrations and inflammation, as measured by the peak CRP in hospitalised influenza patients (Spearman’s ρ = −0.223; p = 0.007)." (PMID 39685701, 2024). "Children with severe influenza with CRP ≥ 7.57 mg/L, Serum IL-6 ≥ 9.84 pg/ml, Days from onset of Flu symptoms to hospitalization ≤4.5 days, CSF-TP ≥ 194.8 mg/L and FluA had a significantly increased risk of febrile seizures." (PMID 39507495, 2024). "The leukocyte count and C-reactive protein level are mostly normal in neonates infected with influenza." (PMID 39294774, 2024). "In our study, the leukocyte count, C-reactive protein level, and procalcitonin level were mostly normal after influenza infection in neonates." (PMID 39294774, 2024). "Over the past two decades, influenza vaccines have served as a model for mild immune system stimulation, based on a modest C-reactive protein response to injection." (PMID 39835131, 2024). "The present study revealed that the CRP level in the FC group was significantly greater than that in the NFC group, demonstrating that CRP is an important inflammatory indicator of severe influenza combined with febrile seizures." (PMID 39507495, 2024). "The effect of age on CRP response is the most likely explanation for our sample’s larger CRP response to influenza vaccination." (PMID 38100425, 2023). "Several studies have utilized influenza vaccines as a model of mild stimulation of the immune system and CRP as a sensitive measure of inflammation induced by that stimulus." (PMID 38100425, 2023). "It has been shown that the reduction in HRV that occurs after influenza vaccination is closely related to elevated CRP levels." (PMID 37241084, 2023). "One point brought forth for discussion among the panel was the potential utility for combined POC testing platforms, with one machine performing multiple POC tests such as CRP, rapid influenza/strep, and white blood cell count." (PMID 36673130, 2023). "We based the timing of our RMR measurements on when we expected CRP to peak (two days after influenza vaccination) using existing literature, but it is possible that changes in RMR would occur at a different time than changes in CRP." (PMID 38100425, 2023). "In contrast, Tsai and colleagues reported CRP concentrations only 7% above baseline seven days following influenza vaccination." (PMID 38100425, 2023). "Lane-Cordova and colleagues reported that even compared to elderly adults with low baseline CRP concentrations, young adults experienced a greater elevation in CRP from baseline after receiving an influenza vaccine." (PMID 38100425, 2023).
influenza (continued). "Both PCT and CRP levels provide valuable information about the prognosis of influenza and SARS-CoV-2 pneumonia." (PMID 36671362, 2023). "This review updates the clinical value of the most widely used biomarkers in daily practice, PCT and CRP, in Influenza and SARS-CoV-2 pneumonia." (PMID 36671362, 2023). "Our results are in line with a study from Spain, where they found elevated WBC and higher CRP levels in RSV infected patients compared to influenza." (PMID 35572955, 2022). "The results suggested that CRP was related to the viral clearance and antibody response in influenza infection." (PMID 36275680, 2022). "Similar to influenza patients, elevated levels of C-reactive protein (CRP) and also procalcitonin were found to serve as good predictors of severe outcomes." (PMID 35883640, 2022). "Our previous study showed that CRP joined in mediating immunopathological lesions in severe influenza." (PMID 36275680, 2022). "To observe the correlation of CRP with the local immune response of lung in mice to influenza infection, we quantified the relative expression levels of 6 immune checkpoint mRNAs in lung tissues of mice, including GITR, BTLA, TIM-3, PD-1, CTLA-4, and LAIR-1." (PMID 36275680, 2022). "Apart from sIgA, C-reactive protein, interleukin, and antibody titers in response to the influenza vaccine are other biomarkers feasible for measuring immune function in workplace MBIs." (PMID 35627765, 2022). "We found that patients with influenza had statistically higher levels of CRP, PCT, LDH, HBDH, and ESR, but lower levels of Alb and Hct on univariate analysis." (PMID 34859002, 2021). "During three consecutive influenza seasons, 281 patients in total were recruited, with CRP results available for 277 patients." (PMID 34850657, 2021). "We enrolled children with respiratory illness presenting to a clinic in southwestern Uganda and performed testing for influenza, Streptococcus pneumoniae, C-reactive protein, and procalcitonin on-site." (PMID 34817224, 2021). "which, to our knowledge, is the only other study investigating CRP as a predictor for recovery time in influenza patients." (PMID 34850657, 2021). "As expected, the median CRP was lower in our study compared to a study of hospitalized patients with influenza." (PMID 33174788, 2020). "Both serum CRP level (117.6 ± 88.1 vs. 78.5 ± 75.2, P = 0.017) and IL-6 level (133.5 ± 149.2 vs. 69.9 ± 100.0, P = 0.021) of severe influenza patients with aspergillosis were greatly higher than those without aspergillosis." (PMID 33537328, 2020). "Other studies have found that among hospitalized influenza patients CRP correlated with hypercytokinemia, acute respiratory distress syndrome, admission to intensive care unit or poor outcome." (PMID 33174788, 2020). "Patients of the influenza subgroup had significantly higher CRP levels and patients of the NCNI subgroup showed significantly higher leucocyte counts, each compared with the other subgroups." (PMID 33379386, 2020). "Our data also showed rapidly increased secretion of IL-6 and CRP in severe influenza patients with aspergillosis than those with influenza alone." (PMID 33537328, 2020). "IL-6 and CRP were the synthesis of pro-inflammatory cytokines released from the epithelial cells invaded by influenza and resulted in further alveolar damage according to enhance phagocytosis of immune cells and activate a series of innate immunoresponses." (PMID 33537328, 2020). "C-reactive protein (CRP) is an acute-phase reactant downstream of the pro-inflammatory cytokines released during influenza infection." (PMID 30288556, 2019). "Receiver operating characteristic analysis for differentiation between CAP and influenza patients showed the highest AUC for CRP (AUC = 0.849), followed by WBC (AUC = 0.680) and neopterin (AUC = 0.663)." (PMID 31489989, 2019). "C-reactive protein, serum amyloid A and cortisol levels were all found to be elevated during influenza infection." (PMID 22022504, 2011).
influenza (continued). "Laboratory features evaluated included lymphocyte count, C-reactive protein (CRP), nasopharyngeal and lower respiratory tract pandemic influenza (H1N1) 2009 PCR results." (PMID 20877727, 2010). "Furthermore, a 2019–2020 study in Turkey identified increased CRP (OR: 7.650; p = 0.002) as a key predictor of influenza diagnosis compared to COVID-19." (PMID 40142409, 2025). "Usually, CRP isfound to be elevated in adeno virus and severe Influenza infections." (PMID 38712005, 2024). "Studies have shown that CRP levels are significantly increased in children with severe influenza infection, which may be a potential indicator for identification and severity assessment of children with influenza." (PMID 39949573, 2024). "Notably, our earlier study has indicated that severe group of children with influenza expressed much higher levels of CRP and SAA, indicating more severe inflammatory response." (PMID 38166827, 2024). "Several panel members felt that combining CRP POC testing with diagnostic tests for SARS-CoV-2, influenza, or strep A testing could be valuable, especially if these molecular tests could also deliver POC results." (PMID 36673130, 2023). "Notably, besides SARS-CoV-2 rapid tests, only relatively few German GPs surveyed in our study utilize POCTs for infectious diseases, such as CRP (utilized by less than 20% of GPs), influenza (15%), RSV (< 5%) and procalcitonin (< 5%)." (PMID 37038122, 2023). "By using a within-individual design to examine the relationship between RMR and CRP in response to mild immune system stimulation by influenza vaccination, this project aims to gain further insight into how humans evolved to allocate energy resources during immune events." (PMID 38100425, 2023). "Likewise, serum CRP concentrations were increased after the influenza challenge, however, the response was attenuated or delayed in BCG-vaccinated pigs two days after inoculation." (PMID 37520542, 2023). "For instance, infection with influenza virus associated with increased CRP levels can lead to altered clozapine metabolism, whereas vaccination against influenza has not shown such effects." (PMID 38058314, 2023). "RMR and CRP at baseline, two days, and seven days after influenza vaccination." (PMID 38100425, 2023). "Laboratory workup was significant for a negative rapid influenza test but a positive respiratory pathogen polymerase chain reaction test for influenza B. His C-reactive protein was elevated at 102.0 milligrams per deciliter (mg/dL) (reference range: 0.0–9.9 mg/dL)." (PMID 36049203, 2022). "Therefore, significantly higher CRP values on hospital admission were detected in influenza-positive subjects after comparing those groups of patients." (PMID 35237386, 2022). "CRP is a double sword in immune regulation of influenza infection in which IL-17 and immune checkpoint may be involved." (PMID 36275680, 2022). "In addition to examining IL-6 alone, we looked at the combination of IL-6 and serum C-reactive protein (CRP) to assess influenza severity." (PMID 34692664, 2021). "Significantly higher levels of CRP (> 40 mg/L) could be detected from patients with bacterial and influenza viral coinfection comparing to that of patients with sole influenza viral infection." (PMID 33816347, 2021). "However, we are reassured that the group who was lost to follow-up was similar to the 90% who were reached in regard to age, home location, sex, influenza test result, CRP, and PCT." (PMID 34817224, 2021). "CRP was also found to be related to AKI in a previous study of influenza patients." (PMID 33922592, 2021). "Rapid influenza diagnostic test–negative patients had a higher percentage of localized infiltrates on chest radiograph, a higher C-reactive protein level, and a higher SOFA score." (PMID 32876004, 2020).
influenza (continued). "Combinations of newer influenza tests with other POCTs, C-reactive protein, for example, may help better identify patients with bacterial coinfections and give clinicians confidence to conserve antibiotics." (PMID 30285232, 2019). "As CRP acts an intermediate factor in the relationship between over-synthesis of serum cytokines and severe influenza, it can be suggested that it can be employed as a biomarker to predict the likelihood of an H1N1-infected patient to develop severe H1N1 influenza." (PMID 30288556, 2019). "After four days, she presented the same symptoms, and a biological assessment was done that confirmed the clinical diagnosis of flu: her white blood cell count was 9540 cells/mm3 with 69.7% neutrophils, hemoglobin at 11 g/dL, platelet count at 288,000/mm3, C-reactive protein (CRP) was 2.3 mg/L." (PMID 28449653, 2017). "In contrast during acute influenza the concentration of CRP increased significantly." (PMID 24893655, 2014). "CRP levels were also higher in mixed involving influenza than in viral CAP due to influenza virus." (PMID 25073709, 2014). "However, plasma-CRP was > 100 mg/L in some of the influenza patients, and < 100 mg/l for 14 of the 15 subacute bacterial tuberculosis and borreliosis patients, thus showing no reliable discrimination between viruses and bacteria." (PMID 20626864, 2010). "Notably, in influenza patients the presence of Aspergillus spp in the gut correlates positively with levels of the systemic inflammatory marker C-reactive protein, while the presence of Mucoromycota correlate negatively with C-reactive protein and procalcitonin." (PMID 39193472, 2024). "Also, previous research has found that RMR and CRP concentrations are correlated at baseline, but, given that influenza vaccination is a mild immune stimulus, changes in CRP may have been too small to result in measurable increases in RMR." (PMID 38100425, 2023). "Hence, our results here indicated that CRP might play an important role in the immune balance of influenza infection, and the role may be a double-edged sword in influenza infection, overexpression or deficiency of CRP would be a disadvantage to the infection." (PMID 36275680, 2022). "However, the detailed response pathway of CRP to the disease is still unknown, although CRP is related to the outcome of severe influenza disease and joined in the mediation of immunopathological lesions." (PMID 36275680, 2022). "However, specific laboratory testing capacity was more available in provincial hospitals than in district hospitals, for example, for blood and sputum culture, inflammatory markers (C-reactive protein and procalcitonin), lactate, arterial blood gas and influenza A and B antigen detection." (PMID 35251746, 2021). "In addition to routine clinical evaluation, we performed influenza and Streptococcus pneumoniae antigen testing and measured levels of C-reactive protein, procalcitonin, and lactate in the clinic’s laboratory, and conducted a follow-up assessment by phone 7 days later." (PMID 34817224, 2021). "Despite many findings suggesting a role of CRP in severe outcome of influenza infection, no systematic analysis was conducted to examine the association between the two conditions and the potential of CRP to be employed as a biomarker to predict the severity of infection." (PMID 30288556, 2019). "More recent papers also reported a lower number of leucocytes and a higher value of the CRP for SARS-CoV-2 infection, but influenza patients in our database expressed lower number of lymphocytes and higher CRP." (PMID 40871340, 2025). "In summary, the differences in traditional indicators of inflammation (leukocytes, CRP and PCT), cytokines and the nCD64 index in the peripheral blood of pregnant women with bacterial infection or influenza A during the influenza season were investigated." (PMID 37638092, 2023).